HLA-C (major histocompatibility complex, class I, C)
Description:
Antigen-presenting major histocompatibility complex class I (MHCI) molecule with an important role in reproduction and antiviral immunity. In complex with B2M/beta 2 microglobulin displays a restricted repertoire of self and viral peptides and acts as a dominant ligand for inhibitory and activating killer immunoglobulin receptors (KIRs) expressed on NK cells. In an allogeneic setting, such as during pregnancy, mediates interaction of extravillous trophoblasts with KIR on uterine NK cells and regulate trophoblast invasion necessary for placentation and overall fetal growth. During viral infection, may present viral peptides with low affinity for KIRs, impeding KIR-mediated inhibition through peptide antagonism and favoring lysis of infected cells. Presents a restricted repertoire of viral peptides on antigen-presenting cells for recognition by alpha-beta T cell receptor (TCR) on HLA-C-restricted CD8-positive T cells, guiding antigen-specific T cell immune response to eliminate infected cells, particularly in chronic viral infection settings such as HIV-1 or CMV infection. Both the peptide and the MHC molecule are recognized by TCR, the peptide is responsible for the fine specificity of antigen recognition and MHC residues account for the MHC restriction of T cells (By similarity). Typically presents intracellular peptide antigens of 9 amino acids that arise from cytosolic proteolysis via proteasome. Can bind different peptides containing allele-specific binding motifs, which are mainly defined by anchor residues at position 2 and 9. Preferentially displays peptides having a restricted repertoire of hydrophobic or aromatic amino acids (Phe, Ile, Leu, Met, Val and Tyr) at the C-terminal anchor. ALLELE C*01:02: The peptide-bound form interacts with KIR2DL2 and KIR2DL3 inhibitory receptors on NK cells. The low affinity peptides compete with the high affinity peptides impeding KIR-mediated inhibition and favoring lysis of infected cells. Presents to CD8-positive T cells a CMV epitope derived from UL83/pp65 (RCPEMISVL), an immediate-early antigen necessary for initiating viral replication. ALLELE C*04:01: Presents a conserved HIV-1 epitope derived from env (SFNCGGEFF) to memory CD8-positive T cells, eliciting very strong IFNG responses. Presents CMV epitope derived from UL83/pp65 (QYDPVAALF) to CD8-positive T cells, triggering T cell cytotoxic response. ALLELE C*05:01: Presents HIV-1 epitope derived from rev (SAEPVPLQL) to CD8-positive T cells, triggering T cell cytotoxic response. ALLELE C*06:02: In trophoblasts, interacts with KIR2DS2 on uterine NK cells and triggers NK cell activation, including secretion of cytokines such as GMCSF that enhances trophoblast migration. ALLELE C*07:02: Plays an important role in the control of chronic CMV infection. Presents immunodominant CMV epitopes derived from IE1 (LSEFCRVL and CRVLCCYVL) and UL28 (FRCPRRFCF), both antigens synthesized during immediate-early period of viral replication. Elicits a strong anti-viral CD8-positive T cell immune response that increases markedly with age. ALLELE C*08:01: Presents viral epitopes derived from CMV UL83 (VVCAHELVC) and IAV M1 (GILGFVFTL), triggering CD8-positive T cell cytotoxic response. ALLELE C*12:02: Presents CMV epitope derived from UL83 (VAFTSHEHF) to CD8-positive T cells. ALLELE C*15:02: Presents CMV epitope derived from UL83 CC (VVCAHELVC) to CD8-positive T cells, triggering T cell cytotoxic response.
Synonyms: HLAC; D6S204; HLA-JY3; HLC-C; MHC; PSORS1
Tractability: Antibody: UniProt places it where antibodies can reach, with high confidence; its Gene Ontology location is reachable by antibodies, with high confidence; UniProt predicts a signal peptide or a membrane-spanning region. PROTAC: ubiquitination databases record sites on it.
Target class: Surface antigen
Safety:
Unwanted effects reported when the protein is acted on. In parentheses: how it was acted on, where the effect was seen, and who reports it.
DRESS Syndrome or SJS/TEN (source: ClinPGx)
drug hypersensitivity, cutaneous adverse reactions (source: ClinPGx)
hypersensitivity reactions (source: ClinPGx)
liver injury (source: ClinPGx)
respiratory failure (source: ClinPGx)
severe cutaneous adverse reactions (source: ClinPGx)
severe cutaneous adverse reactions (SCARs) (source: ClinPGx)
simple rash (source: ClinPGx)
Stevens-Johnson syndrome/toxic epidermal necrolysis (SJS/TEN) (source: ClinPGx)
Stevens-Johnson syndrome/toxic epidermal necrolysis (SJS/TEN) or maculopapular exanthema (MPE) (source: ClinPGx)
thrombocytopenia (source: ClinPGx)
toxic liver disease (source: ClinPGx)
Gene: Protein-coding gene on chromosome 6 (31,268,749 to 31,272,130, reverse strand). Ensembl gene ENSG00000204525.
Subcellular location: Cell membrane; Endoplasmic reticulum membrane
Pathways (Reactome):
Immune System: Antigen Presentation: Folding, assembly and peptide loading of class I MHC; DAP12 interactions; ER-Phagosome pathway; Endosomal/Vacuolar pathway; Immunoregulatory interactions between a Lymphoid and a non-Lymphoid cell; Interferon alpha/beta signaling; Interferon gamma signaling; Neutrophil degranulation
Disease: SARS-CoV-2 activates/modulates innate and adaptive immune responses
Gene Ontology:
Molecular function: peptide antigen binding; protein binding; receptor ligand activity; TAP binding; beta-2-microglobulin binding; signaling receptor binding
Biological process: antigen processing and presentation of endogenous peptide antigen via MHC class I via ER pathway, TAP-independent; antigen processing and presentation of exogenous peptide antigen via MHC class Ib; positive regulation of natural killer cell mediated cytotoxicity; antigen processing and presentation of endogenous peptide antigen via MHC class Ib; immune response; positive regulation of T cell mediated cytotoxicity; regulation of natural killer cell mediated immunity; antigen processing and presentation; signal transduction
Cellular component: cell surface; endoplasmic reticulum; extracellular exosome; extracellular region; Golgi apparatus; membrane; MHC class I protein complex; MHC class Ib protein complex; plasma membrane; early endosome membrane; ER to Golgi transport vesicle membrane; external side of plasma membrane; Golgi membrane; lumenal side of endoplasmic reticulum membrane; phagocytic vesicle membrane; recycling endosome membrane; secretory granule membrane; endoplasmic reticulum membrane
Genetic constraint (gnomAD): Loss-of-function variants: 4 observed, 1.28 expected, observed/expected ratio (o/e) 3.12. That is too few expected variants to judge how well the gene tolerates losing a copy. Missense variants: 117 observed, 40.96 expected, observed/expected ratio (o/e) 2.86. Synonymous variants: 44 observed, 18.73 expected, observed/expected ratio (o/e) 2.35.
Homologues: Orthologues: chimpanzee PATR-B (87% identical), macaque Mamu-B (76% identical), zebrafish si:ch211-147g22.4 (17% identical), zebrafish mhc1lia (13% identical). Paralogues in human: HLA-B (86% identical), HLA-A (81% identical), HLA-F (74% identical), HLA-G (74% identical), HLA-E (74% identical), MR1 (34% identical), HFE (34% identical), AZGP1 (28% identical), FCGRT (27% identical), MICB (26% identical), MICA (25% identical), CD1B (22% identical), and 10 more.
Diseases named in the same sentence as HLA-C in open-access papers:
HLA-C is named in the same sentence as 426 diseases in open-access papers, as found by Europe PMC text mining. Sharing a sentence is not in itself a finding about the gene and the disease. The quoted sentences say what the papers report.
psoriasis (232 papers, 2006 to 2026). An autoimmune condition characterized by red, well-delineated plaques with silvery scales that are usually on the extensor surfaces and scalp. "HLA-C*01:02 has been identified as a risk allele for psoriasis in a Chinese population, whereas HLA-C*18:01 has been associated with difficult-to-treat psoriasis in a Caucasian European population." (PMID 41512531, 2026). "Consistent with previous research, the authors found that the HLA-C*06:02g allele was one of the strongest genetic markers linked to psoriasis, which aligns with global data on its role in determining the early onset and increased severity of the disease." (PMID 41512531, 2026). "To date, over 80 susceptibility genes for psoriasis have been identified, the most prominent of which is the HLA-C*07:02 locus associated with the onset of psoriasis." (PMID 40142947, 2025). "Consistently, in a preliminary analysis, the healing of psoriasis through UVB phototherapy was associated with a loss of HLA-C expression on lesional melanocytes." (PMID 40243413, 2025). "Other HLA class I alleles associated with a risk of psoriasis are HLA-C*07:01, HLA-C*07:02, HLA-C*07:04, and HLA-B*27:05, with HLA-B*27:05 and HLA-C*06:02 being phenotype-defining risk alleles also for psoriatic arthritis." (PMID 41440022, 2025). "Studies have implied that HLA-C*06:02 (on PSORS1 6p21.33) is a major susceptibility gene locus for psoriasis, whereas null mutations of the FLG gene (1q21.3) have been suggested to increase the risk of AD." (PMID 40920623, 2025). "Less frequently associated HLA-class I-alleles which also confer susceptibility to psoriasis are HLA-C*07:01, HLA-C*07:02, HLA-C*12:02, HLA-C*07:04, HLA-B*27, and HLA-B*57." (PMID 40243413, 2025). "Early-onset psoriasis is seen as more severe and is linked to the presence of HLA-C*06, in contrast to late-onset psoriasis." (PMID 39077241, 2024). "Prior studies have found that HLA-C*01:02-positivity has been associated with a higher frequency of erythrodermic psoriasis in a Chinese cohort and higher frequency of pustular psoriasis in a Japanese cohort." (PMID 39261909, 2024). "Many studies on psoriasis cardiometabolic comorbidities have focused mainly on its relationship with the HLA-C*06:02 allele." (PMID 39261909, 2024). "Remarkably, S. cerevisiae antigens drive pathogenic T cell responses in Crohn’s disease, which is associated with psoriasis and shares HLA-C*06:02 as a risk gene." (PMID 38524140, 2024). "ATP6V1G2 is situated in the HLA region, akin to the psoriasis susceptibility region containing HLA-C, such as TNF." (PMID 39026678, 2024). "ADAMTS-like protein 5 (ADAMTSL5), a melanocyte protein, was identified as an autoantigen in psoriasis presented by HLA-C*06:02, the main psoriasis risk gene." (PMID 38642273, 2024). "HLA-C*6:02 is the major psoriasis risk allele that is located in psoriasis susceptibility locus 1 (PSORS1) within the short arm of chromosome 6p21." (PMID 37569685, 2023). "A prior study showed that with each additional HLA-C*06:02 risk allele (tagged by rs10484554), there was a 206% elevated risk of psoriasis." (PMID 37323656, 2023). "Amongst psoriasis risk-related leukocyte antigens, HLA-C*07:01, C*07:02, and B*27 utilize the same anchor residues with HLA-C*06:02, have overlapping peptide-binding properties, and belong to the same HLA supertype." (PMID 36826011, 2023). "PSOR1, located in the HLA-C gene, has been accepted as the major susceptibility gene linked to psoriasis." (PMID 36826011, 2023). "Among the HLA types, HLA-C*6:02 has emerged as the strongest genetic risk factor for psoriasis, with the rs10484554 SNP within the gene showing a significant association." (PMID 37569685, 2023). "T1P has been associated with a family history of psoriasis with involvement of HLA-C*06:02 whereas T2P is less associated with a positive family history or involvement of HLA-C*06:02." (PMID 37323656, 2023).
psoriasis (continued). "HLA-C*06 and HLA-C*07 allele frequencies were the highest in the three psoriasis clinical phenotypes." (PMID 36826011, 2023). "Overall, we provide a structural basis for understanding the engagement of melanocyte antigen-presenting cells by a TCR implicated in psoriasis while simultaneously expanding our knowledge of how TCRs engage HLA-C." (PMID 37330172, 2023). "Within the MHC, the allele HLA-C*0602 exhibits the most robust correlation with psoriasis and is considered the PSORS1 risk variant." (PMID 37628670, 2023). "Particularly, individuals carrying the HLA-Cw*06 allele (also known as HLA-C*06:02) have a 10–20-fold increased risk of psoriasis." (PMID 37372997, 2023). "In a cohort of Greek patients with moderate-to-severe psoriasis (n = 228), the rs10484554 polymorphism in the HLA-C gene was associated with a better response to anti-TNF-α, as well as the HLA-A-rs610604 polymorphism with a better response to adalimumab." (PMID 37372997, 2023). "In a recent review, Dand and collaborators discussed the genetic basis of psoriasis and highlighted the contribution of HLA-C*06:02, a variant of the class I major histocompatibility complex (MHC-I) gene, as the main determinant of early psoriasis incidence." (PMID 36837912, 2023). "Psoriasis is a chronic inflammatory skin disease commonly classified into two subgroups depending on the presence of the HLA-C*0602 allele and the onset age of disease symptoms." (PMID 37834254, 2023). "There are genes that are strongly associated with a higher risk of developing psoriasis, such as HLA-C*06:02." (PMID 37569685, 2023). "In that sense, a few studies have found an association between HLA-C∗06 and a longer psoriasis-arthritis latency time, as well as a positive association between several HLA-C antigens and different features of psoriatic disease." (PMID 35127937, 2022). "A recent study revealed that ERAP1 causes psoriasis by affecting HLA-C production via melanocyte autoantigens." (PMID 36425068, 2022). "Apart from the well-known association between HLA-C∗06 and type I psoriasis (familial, severe, early-onset), little is known about the role of HLA-C alleles on the phenotypic expression of psoriatic disease." (PMID 35127937, 2022). "Distinct HLA-class I alleles with a strong associations with autoimmune diseases are HLA-B*27 that is associated with ankylosing spondylitis, HLA-C*06:02 with psoriasis, and HLA-B*51 with Behçet’s disease." (PMID 36700227, 2022). "In psoriasis, the strongest genetic association is with HLA-C*06:02, thought to be mediated by HLA-C*06:02-restricted T cells." (PMID 35587797, 2022). "ERAP1 is more likely to be present in individuals carrying the HLA-C susceptibility allele, with the first and most important psoriasis susceptibility gene identified." (PMID 36425068, 2022). "For the psoriatic autoimmune response, we had initially identified 6 peptides from human proteins through homology search that were presented by the psoriasis risk allotype, HLA-C*06:02, and stimulated the pathogenic psoriatic Vα3S1/Vβ13S1 TCR." (PMID 36700227, 2022). "This suggests different trimming requirements of HLA-I molecules associated with psoriasis in HLA-C*06:02-positive and HLA-C*06:02-negative patients, respectively." (PMID 35769458, 2022). "Among hundreds of loci and genes associated with psoriasis, PSORS1 is the most prominent locus identified on the chromosome 6p21, in the region coding for HLA-C*06:02." (PMID 35883760, 2022). "To date, only HLA-C*06:02 has been consistently reported to associate with ustekinumab response in psoriasis." (PMID 35154085, 2021). "The HLA-Cw*06 alleles (also known as HLA-C*06:02) have been shown to confer a high risk of suffering from psoriasis, but its association with response to anti-TNF drugs and cytokine inhibitors is contradictory." (PMID 33921427, 2021). "In particular, the HLA-Cw*06 alleles (also known as HLA-C*06:02) have been described as the first-factor risk of psoriasis." (PMID 33921427, 2021).
psoriasis (continued). "A common functional synonymous mutation Y319Y in CDSN had previously been associated with psoriasis independently of HLA-C alleles." (PMID 34879060, 2021). "The locus demonstrating the strongest effect on risk is the MHC region, with several alleles of HLA-C and HLA-B conferring a 2-4-fold increased risk of psoriasis." (PMID 34177931, 2021). "HLA-C*06:02 presence in psoriasis patients is associated with greater plaque severity (measured by the extent of inflammation and body area covered) and earlier disease onset." (PMID 34639182, 2021). "First, we collected 45 experimentally identified psoriasis susceptibility gene loci and their target genes, including the primary susceptibility gene loci and HLA-C*06:02 37,38." (PMID 33958582, 2021). "Candidate gene studies have identified the HLA-C*06:02 allele as being associated with better ustekinumab responses in both European and Chinese patients with psoriasis." (PMID 35154085, 2021). "Human leukocyte antigen (HLA) genes are the most substantial contributors to psoriasis genetic susceptibility, particularly the HLA-C*06:02 allele." (PMID 34639182, 2021). "In our study, neonatal HLA-C expression in both myeloid cells and T cells was causally associated with multiple autoimmune diseases such as psoriasis, SLE, and primary biliary cirrhosis." (PMID 32724101, 2020). "Noteworthy, HLA-B*27, which is among the HLA class I alleles predisposing to Psoriasis, presents an immunopeptidome partly overlapping with that of HLA-C*06:02 characterized by shared anchor residues at P2 and P9." (PMID 33348540, 2020). "SNP: single nucleotide polymorphism, HLA: human leukocyte antigens, PASI: Psoriasis Area and Severity Index, IL: interleukin * Therapeutic success increases in HLA-C*06:02 positive patients." (PMID 33419370, 2020). "Recent studies confirmed the importance of HLA-C*06:02 in genetic susceptibility of psoriasis along with its effect on treatment responses." (PMID 31902555, 2020). "In our analysis of resting neonatal T cells, the largest causal effect of HLA-C expression was for psoriasis." (PMID 32724101, 2020). "Since there are limited numbers of studies that have been made in Turkey for genetic susceptibility factors in patients with psoriasis, we aimed to investigate frequency of HLA-C alleles in the Turkish population." (PMID 31341424, 2019). "LL37 and ADAMTSL5 are recognized by T-cells after binding to HLA-C*06:02 underlining the role of distinct HLA genotypes in the pathogenesis of psoriasis." (PMID 31417571, 2019). "While most, if not all, autoimmune diseases are linked with certain HLA alleles, HLA-C*06:02 is the predominant psoriasis risk gene." (PMID 31402919, 2019). "HLA-B*27 was associated with early development of PsA among patients with psoriasis, whereas the presence of HLA-C*06 was associated with a delayed onset of PsA29." (PMID 31583079, 2019). "They examined the structure of the receptor-ligand complex formed by the HLA-C*06:02 allele product and pVR autoantigen peptide from psoriasis patients." (PMID 29666398, 2018). "HLA-C, being part of the major histocompatibility complex on chromosome 6 has also been associated with various auto-immune diseases such as psoriasis, Crohn’s disease and atopic-dermatitis." (PMID 28990592, 2018). "The strong psoriasis risk of HLA-C*06:02 allele has been validated in worldwide populations including Europeans, East, and South Asians, with odds ratios of as high as 3.0–10.0." (PMID 29760713, 2018). "This association (similarly to HLA-C*06:02) is strongly dependent on age at disease onset and concerns predominantly type I psoriasis." (PMID 29589160, 2018). "Defining the functional role of the main psoriasis risk gene, HLA-C*06:02, allowed for re-defining the architecture of the pathogenic psoriatic immune response." (PMID 29760713, 2018). "They indicate that HLA-C*06:02 predisposes to psoriasis by mediating an autoimmune response against melanocytes through autoantigen presentation." (PMID 29760713, 2018).